BTK (Bruton tyrosine kinase)
Diseases named in the same sentence as BTK in open-access papers (continued):
Sharing a sentence is not in itself a finding about the gene and the disease.
COVID-19 (continued). "At the time of COVID-19 diagnosis, 34.3% of patients were receiving active CLL therapy, most commonly Bruton tyrosine kinase inhibitors (BTKi’s) (54.9%)." (PMID 36028857, 2022). "The protective effects of BTK inhibitors have also been observed in CLL patients with COVID-19, as the hospitalization rate and duration for severe COVID-19 is lower and shorter for CLL patients on ibrutinib versus those on other regimens or off treatment." (PMID 34778053, 2021). "Bruton's tyrosine kinase (BTK) inhibitors, drugs utilized in cancer, are being repurposed for severe acute respiratory syndrome coronavirus-2 (SARS-CoV-2) (COVID-19)." (PMID 33441177, 2021). "Bruton tyrosine kinase (BTK) inhibitors have been suggested and tested as a treatment for COVID-19, specifically for mitigation of the cytokine storm." (PMID 33785634, 2021). "In humans, effective suppression of the NLRP3/IL-1 axis by BTK inhibitors, and thus a positive regulatory effect of BTK on NLRP3, was instead suggested by a recent off-label trial of acalabrutinib in COVID-19 patients." (PMID 33718366, 2021). "Other anti-inflammatory treatments now being tested clinically for their use against COVID-19 are Janus kinase (JAK) and Bruton's tyrosine kinase (BTK) inhibitors." (PMID 32903476, 2020). "While BTK inhibitors interfere with B cell activation and could potentially lower anti-viral antibody titers, this concern may be mitigated by the timing of administration to patients with severe COVID-19, who are typically hospitalized 7 or more days following initial infection." (PMID 32503877, 2020). "Interestingly, some agents were found to have anti-cytokine storm effects, which have shown promise in patients with COVID-19 (e.g., the Janus kinase (JAK) inhibitors and Bruton’s tyrosine kinase (BTK) inhibitors)." (PMID 37643201, 2023). "Further, a Bruton tyrosine kinase (BTK) inhibitor was also found to reduce BTK-dependent activation of NF-κB and NLRP3 inflammasome, which suppressed pro-inflammatory factors production and COVID-19 cytokine storm, thereby improving the prognosis of COVID-19 patients." (PMID 37065192, 2023). "Furthermore, after the identification of an FDA-approved inhibitor of the NLRP3-specific regulatory protein Bruton ́s tyrosine kinase (BTK), the application of the commercially available BTK inhibitor ibrutinib in severe COVID-19 cases was investigated." (PMID 35626754, 2022). "The analyses of these 7 gene expression levels between different clinical features suggested that BTK, SDK1, CCL20, LDHA, and ZIC5 may serve as effective biomarkers for screening and characterizing patients with LUAD/COVID-19 at different stages." (PMID 35733175, 2022). "Furthermore, the downstream factors of TLR7 and BTK in TLR pathway, such as MYD88, IRF7, NFKB1, and JUN, and cytokines (TNF, IL1B, and IL18) were elevated in men with severe COVID-19." (PMID 34330889, 2021). "Several BTK inhibitors (e.g., acalabrutinib and ibruitinib, which blocks TLR7-dependent NF-κB activation in monocytes) have been shown to be potentially promising in treatment of patients with severe COVID-19." (PMID 34330889, 2021). "Applying these criteria resulted in two top predicted sex-biased genes, including TLR7 and Bruton tyrosine kinase (BTK), which may explain the sex-specific disease severity of COVID-19." (PMID 34330889, 2021). "In fact, the clinical efficacy of BTK inhibitors in GvHD and COVID-19, and the reported role of the NLRP3/IL-1 axis in these disease states lend support to the notion that BTK-inhibitor therapy for NLRP3 inhibition warrants further preclinical and clinical exploration." (PMID 33718366, 2021). "While it has been hypothesized that the BTK inhibitor ibrutinib might have protective effects against COVID-19 by attenuating hyperinflammatory responses, there is currently no data on COVID-19 in patients receiving venetoclax-based treatments." (PMID 32601378, 2020).
COVID-19 (continued). "Notably, blood B cells did not have evidence of BTK activation, suggesting that monocytes/macrophages may be the relevant in vivo target of acalabrutinib in COVID-19." (PMID 32503877, 2020).
diffuse large B-cell lymphoma (63 papers, 2014 to 2026). "Here, by a combination of structural modeling, in vitro assays, and deep phospho-tyrosine proteomics, we demonstrated that four clinically observed BTK mutations—C481F, C481Y, C481R, and L528W—inactivated BTK kinase activity both in vitro and in diffused large B-cell lymphoma (DLBCL) cells." (PMID 36183831, 2022). "Currently, combining chemotherapy with Bruton tyrosine kinase inhibitors (BTKi) has demonstrated significant effectiveness in treating patients with diffuse large B-cell lymphoma." (PMID 37925380, 2023). "Bruton tyrosine kinase inhibitors are found to be effective in the treatment of primary central nervous system diffuse large B cell lymphoma." (PMID 33968786, 2021). "And more importantly, L18I can cause the decrease of BTK protein level in mutant diffuse large B-cell lymphoma (DLBCL) tumor, thereby effectively inhibiting the growth of the tumor in vivo and overcoming the tumor resistance to Ibrutinib caused by the C481 mutation of BTK." (PMID 34249939, 2021). "However, responses of the diffuse large B-cell lymphoma (DLBCL) to inhibitors of BTK (BTKi) are infrequent, highlighting the need to identify mechanisms of resistance to BTKi as well as predictive biomarkers." (PMID 29690649, 2018). "Tirabrutinib, a Bruton tyrosine kinase (BTK) inhibitor, has shown efficacy in recurrent or refractory diffuse large B-cell lymphoma (DLBCL)." (PMID 40365248, 2025). "The results showed that ASK120067 dose-dependently suppressed anti-IgM stimulated BTK phosphorylation at Y223 in the diffuse large B-cell lymphoma (DLBCL) cell line SU-DHL-6." (PMID 36588692, 2022). "The first-generation BTK inhibitor ibrutinib shows significant antitumor activity in relapsed/refractory activated B cell-like (ABC) diffuse large B-cell lymphoma (DLBCL)." (PMID 35004280, 2021). "BTK is overexpressed in Diffuse Large B-cell Lymphoma (DLBCL) than normal tissues, but has a lower expression in LUAD and LUSC than normal tissues." (PMID 34187403, 2021). "In the activated B-cell-like (ABC) subtype of diffuse large B-cell lymphoma (DLBCL) an RNA interference genetic screen revealed that BTK is essential for the survival of lymphoma cells with wild-type Caspase recruitment domain family, member 11 (CARD11)." (PMID 34177947, 2021). "In this study, to determine whether BTK inhibitor-based drug combination therapy can benefit the treatment of diffuse large B-cell lymphoma, we play proliferation assay with an appropriate concentration of Apigenin in combination with low-dose Abivertinib in U2932 and OCI-LY10 for 48 hours." (PMID 32127939, 2020). "BTK inhibitors are used to treat B-cell tumors (e.g., diffuse large B-cell lymphoma, DLBCL)." (PMID 40568785, 2025). "Co-targeting of BTK and TXNRD1 is an effective therapeutic strategy to consider for Diffuse large B-cell lymphoma (DLBCL) treatment." (PMID 39744566, 2025). "Moreover, the amplification of BTK expression has been notably observed in diffuse large B-cell lymphoma (DLBCL), correlating with disease aggressiveness and predicting poor prognosis." (PMID 39062757, 2024).
diffuse large B-cell lymphoma (continued). "To this aim, we probed the BTK-expressing diffuse large B-cell lymphoma (DLBCL) cell line TMD867 with DDa-1 at various concentrations and could confirm BTK degradation with sub-μM potency." (PMID 38177131, 2024). "However, in diffuse large B‐cell lymphoma (DLBCL), cell lines of the activated B‐cell‐like (ABC) subtype have been shown to be dependent on BTK signaling, while cell lines of the germinal center B‐cell‐like (GCB) subtype were independent of BTK." (PMID 36051027, 2022). "Relapse on ibrutinib is frequently due to BTK mutations that prevent inhibitor binding and often lead to the development of more aggressive diseases such as relapse/refractory CLL or Richter Transformation (RT) from CLL into diffuse large B-cell lymphoma (DLBCL-RT)." (PMID 35743155, 2022). "VRL, as well as PCNSL, display typically an activated B cell-like (ABC) phenotype of diffuse large B-cell lymphoma (DLBCL), with frequent CD79B and MYD88 mutations, which may represent a strong biological rationale for the use of BTK inhibitors in the treatment of PCNSL and VRL." (PMID 33968786, 2021). "Additionally, pre-clinical evaluation of drug combinations revealed synergy between Bruton’s tyrosine kinase (BTK) and PI3K inhibition in diffuse large B-cell lymphoma." (PMID 26402468, 2015).
leukemia (50 papers, 2014 to 2026). A malignant (clonal) hematologic disorder, involving hematopoietic stem cells and characterized by the presence of primitive or atypical myeloid or lymphoid cells in the bone marrow and the blood. "It is worth noting that Bruton’s tyrosine kinase (BTK) inhibitor ibrutinib used for the treatment of some B cell-associated lymphomas/leukemias has been tested in solid tumors." (PMID 31086070, 2019). "While the PLCG2-mutated leukemia cells were selected for in patients with CLL treated with inhibitors for BTK, the GoF alteration was at same time toxic, thereby resulting in reduced clone sizes compared to non-damaging resistance mutations affecting BTK itself." (PMID 39596040, 2024). "Ibrutinib, and second-generation BTKi’s, such as acalabrutinib and zanubrutinib, form a covalent bond with BTK within its kinase domain at residue C481, causing permanent inactivation of BTK and requiring the leukemia cell to synthesize new enzyme to restore B-cell signaling." (PMID 39048721, 2024). "Inhibiting NFκB in leukemia cells with Bruton tyrosine kinase (BTK) inhibitor ibrutinib had a potent impact, allowing only a quiescent population of malignant cells to survive treatment." (PMID 40643557, 2025). "BTK, a key component of the B-cell receptor signaling pathway, has been targeted in B-cell malignancies, but its role in leukemia is unexplored." (PMID 40300107, 2025). "In the context of leukemia, dysregulation or overactivity of BTK can contribute to the expansion of malignant B cells." (PMID 40486885, 2025). "In this study, we demonstrated a new set of 2,6,9-trisubstituted purine derivatives with broad inhibitory activity on three leukaemia-related tyrosine kinases: Bcr-Abl, BTK and FLT-3-ITD." (PMID 35745866, 2022). "Ibrutinib is an FDA-approved Bruton’s tyrosine kinase (BTK) inhibitor used in the treatment of leukemias." (PMID 35682764, 2022). "Compound 10 having pomalidomide and a phenyl-pyrazole-based BTK inhibitor exhibited potent and selective activity in degradation of BTK in Burkitt lymphoma Ramos and leukemia THP-1 cells." (PMID 32404196, 2020). "According to the literature, spleen tyrosine kinase (SYK), phosphoinositide 3’kinase (PI3K), and Bruton’s tyrosine kinase (BTK) were selected because they have been related to decrease of leukemia cells in preclinical models." (PMID 31861689, 2019). "Since BTK inhibitors are already being used clinically to treat different leukaemias, it is urgent to better characterize the mechanisms by which BTK affects the oncogenic and tumour suppressor pathways, in order to avoid unexpected long-term side effects." (PMID 29290977, 2017). "Therefore, by inhibiting BTK, Ibrutinib reduces the proliferation of these aberrant B cells, thereby helping to manage leukemia consequently, reducing tumors related to CLL." (PMID 40486885, 2025). "Hence, this kinase family includes therapeutic targets for the treatment of inflammatory diseases and leukemia, with BTK being the most intensely studied member and a major drug target." (PMID 35056884, 2022). "The capacity of such signaling molecules to affect phosphorylation ERK1/2 and leukemia-cell proliferation, however, is dependent on kinases such as BTK, which can be inhibited by ibrutinib, potentially accounting for the noted clinical activity of this drug in the treatment of patients with CLL." (PMID 33097837, 2021). "Moreover, the IC50 in TEX and OCI-AML2 leukemia cells were over 10-fold higher than the concentration of ibrutinib required to completely repress BTK phosphorylation and higher than the pharmacologically achievable concentrations in humans." (PMID 26624983, 2016).
leukemia (continued). "The IgH.ETμ mouse model shows that BTK expression is a prerequisite for CLL development whereas the TCL1 mouse model showed that mice with ablation of BTK significantly delayed CLL development but still developed leukemia at rates similar to wild type TCL1 mice treated with ibrutinib." (PMID 33134182, 2020). "Taken together, CG-806 demonstrates superior anti-leukemia activity in vitro and in vivo compared to other FLT3i by suppression of FLT3/BTK/AURK simultaneously." (PMID 36865133, 2023). "In fact, targeting BTK with ibrutinib shows anti-proliferative effects in AML by mediating suppression of FLT3 downstream signaling MAPK, AKT, and NF-κB; and combined inhibition of FLT3 and BTK reportedly has additive anti-leukemia effects." (PMID 36865133, 2023). "Innate platelet dysfunction in CLL patients and the contribution of the leukemia microenvironment to the anti-platelet effect of BTK inhibitors are still not well defined." (PMID 36497231, 2022). "In this study, we examined primary circulating leukemia cells of patients with MCL undergoing treatment with ibrutinib, which is highly effective at inhibiting BCR-signaling through its capacity to inhibit BTK." (PMID 29872501, 2018). "Furthermore, a therapeutic kinase inhibitor directed against all three novel targets, FLT3, BTK, and AURK, may be able to achieve much enhanced anti-leukemia efficacy in the targeted therapy of AML." (PMID 36865133, 2023). "Similarly, the key functions of AKR1C3 in the metabolism of prostaglandins and sex hormones have been related to the development of leukaemia and hormone-related tumours, respectively; thus, AKR1C3 targeting by BTK inhibitors may also counteract carcinogenesis in those tissues overexpressing AKR1C3." (PMID 33322571, 2020). "Our findings confirmed that CG-806 is a pan-FLT3 inhibitor that may benefit from the simultaneous suppression of FLT3, BTK and AURK activation, leading to a promising anti-leukemia effect against AML regardless of their FLT3 status." (PMID 36865133, 2023).
agammaglobulinemia (49 papers, 2004 to 2025). A decreased level of serum immunoglobulins. "XLA is caused by mutations in the Bruton’s tyrosine kinase (BTK) gene and is the most common cause of congenital agammaglobulinemia, accounting for approximately 85% of cases." (PMID 40853601, 2025). "Bruton’s agammaglobulinemia was associated with classic BTK mutations like c.1483G>A, whereas functional B-cell deficiency was connected to BLNK, indicating issues in early B-cell development." (PMID 40806973, 2025). "It has been over 70 yr since Bruton first reported agammaglobulinemia, and 30 yr since the discovery that BTK mutations cause XLA." (PMID 37273190, 2023). "The most frequent main genetic causes of predominantly antibody deficiencies in children infected with SARS-CoV-2 were BTK (n = 41), NFKB2 (n = 4), TNFRSF13B (n = 3), PIK3CD (n = 3), and PIK3R1 (n = 2)." (PMID 37559153, 2023). "Seven disorders were previously classified as IEI, being (i) predominantly antibody deficiencies due to variants in the BTK gene, the most abundant disorders in the cohort." (PMID 37592284, 2023). "X-Linked Agammaglobulinemia, caused by BTK variations, emerged as the most prevalent IEI disorder in the cohort." (PMID 37592284, 2023). "X‐linked agammaglobulinemia (XLA) is the most common form of agammaglobulinemia and is caused by mutations in Btk, which encodes Bruton tyrosine kinase (BTK)." (PMID 37904676, 2023). "The Bruton tyrosine kinase (BTK) is important for B cell receptor (BCR) signaling as well as B cell development and mutations in BTK are the most common cause for hypogammaglobulinemia." (PMID 36524121, 2022). "This paradoxical phenomenon is also seen in T1DM patients suffering from Bruton tyrosine kinase (BTK) mutation, which is an X-linked hereditary disorder that causes Β-cell deficiency, resulting in agammaglobulinemia (XLA)." (PMID 32802890, 2020). "Clinical findings, laboratory results, and BTK mutations in 20 Vietnamese patients with agammaglobulinemia." (PMID 29503650, 2018). "A similar clinical phenotype of agammaglobulinemia or hypogammaglobulinemia is observed in patients with hemizygous variants in BTK, biallelic variants in BLNK, heterozygous gain-of-function (GOF) PIK3CD, or loss-of-function (LOF) PIK3R1 variants, which all encode proteins involved in BCR signaling." (PMID 41607487, 2025). "XLA is a well-characterized IEI caused by germline mutations in the BTK gene, resulting in impaired B cell development, profound hypogammaglobulinemia, and increased susceptibility to bacterial infections, predominantly affecting males and manifesting in early infancy." (PMID 40863427, 2025). "Previous studies demonstrated that rheumatologic involvement is the most frequent manifestation in patients with agammaglobulinemia and investigated the importance of BTK for human B cell tolerance and the role of its deficiency in systemic autoimmune diseases such as RA." (PMID 36790564, 2023). "Pathogenic variants in BTK cause immunodeficiency due to agammaglobulinemia (XLA)." (PMID 36056138, 2022). "Interestingly, P215, who presented with hypogammaglobulinemia, low circulating B cells, and impaired vaccine responses, carried a new hypomorphic variant in the kinase domain of BTK." (PMID 34975878, 2021). "In female patients with agammaglobulinemia, BTK variants may induce XLA through skewed XCI." (PMID 41327272, 2025). "The inspiration for BTK inhibitors can be thought as being the pharmacological simulation of Bruton’s agammaglobulinemia, an X-linked disease which produces, in the case of men, agammaglobulinemia and in the case of women the only lymphocytes that reach development." (PMID 34640501, 2021).